MTOR (mechanistic target of rapamycin kinase)
Diseases named in the same sentence as MTOR in open-access papers (continued):
Sharing a sentence is not in itself a finding about the gene and the disease.
ovarian carcinoma (continued). "In addition, miR-497 and miR-199a were found to quantitatively control mTOR expression to induce apoptosis in ovarian cancer cells." (PMID 38539161, 2024). "Furthermore, estrogen signaling can interact with other pathways that are implicated in ovarian cancer, such as the PI3K/AKT/mTOR pathway." (PMID 38666020, 2024). "Besides, the application of combined targeting of mTOR and ferroptosis have a good prospect in tumors, such as ovarian cancer, triple-negative breast cancer, bladder cancer, etc." (PMID 38583115, 2024). "Daphnetin-induced autophagy and apoptosis may depend on the AMPK/Akt/mTOR pathway in ovarian cancer cells." (PMID 39011506, 2024). "Findings indicated that the protein concentrations of PI3K (pi-PI3K), AKT (pi- AKT) and mTOR (pi-mTOR) were significantly increased in ITGB2-overexpressing ovarian cancer cells (SKOV3), and these increases could be reversed after PI3K and AKT inhibition." (PMID 38345576, 2024). "Additionally, RSV decreases galectin-3 (GAL-3) levels by raising miR-424-3p, thereby inhibiting glycolysis and targeting the AMPK/mTOR signaling pathway to suppress ovarian cancer cell proliferation and induce apoptosis." (PMID 39439517, 2024). "Furthermore, the differential expression of components involved in the mechanistic target of rapamycin (mTOR) pathway seem to connect endometriosis and the development of ovarian cancer." (PMID 38673891, 2024). "The potential oncogenic role of UBE2S is significantly linked to unfavorable prognosis in ovarian cancer patients, and is responsible for the promotion of ovarian cancer development through the regulation of apoptosis and cell cycle via PI3K/AKT/mTOR signaling." (PMID 38312603, 2024). "Similarly, our previous high-throughput Reverse Phase Protein Array (RPPA) observed a compensatory up-regulation of the mTOR pathway following AZD1775 treatment during early stages of ovarian cancer." (PMID 38231277, 2024). "In addition, targeted therapies using tyrosine-kinase inhibitors, MEK inhibitors, and PI3K/mTOR/Akt inhibitors are currently being tested in several ovarian cancer subtypes." (PMID 38673891, 2024). "Moreover, this miRNA directly targets E2F5, a key player in DNA synthesis, negatively regulating the mTOR signaling pathway and hindering the development of ovarian cancer cells." (PMID 38793064, 2024). "We first unmasked that HDAC7 acts as an oncogene in ovarian cancer by promoting AKT/mTOR pathway." (PMID 39431349, 2024). "Studies reported that oridonin could inhibit metastasis of ovarian cancer by inhibiting mTOR pathway." (PMID 38464825, 2024). "Furthermore, a high-throughput proteomic analysis revealed the overexpression of AKT/mTOR pathway molecules and phosphorylated S6 ribosomal protein in small cell lung cancer and ovarian cancer models that exhibit primary resistance to AZD1775." (PMID 38231277, 2024). "Therapeutic targeting of the mTOR pathway may represent the future in preventing ovarian cancer and may offer potential predictive and prognostic biomarkers in EAOCs." (PMID 38893278, 2024). "Hyperactivated PI3K/Akt/mTOR signaling was found in ovarian carcinomas." (PMID 39062784, 2024). "Similarly, in other types of cancers, Tanshinone I induces autophagy by inhibiting the PI3K/AKT/mTOR pathway, thereby mitigating the malignant biological characteristics of ovarian cancer." (PMID 39428922, 2024). "Moreover, miR-1290 overexpression in CAFs also changed EMT markers and promoted mTOR and Akt phosphorylation within ovarian carcinoma cells." (PMID 38402185, 2024). "Significantly, enhanced activation of mTOR signaling has been reported in ovarian cancer." (PMID 38489280, 2024). "More recently, the combination of curcumin and RES significantly sensitized the epithelial ovarian cancer A2780 (cisplatin-sensitive cell line) and A2780-cis (cisplatin-resistant cell line) to cisplatin, thereby inhibiting ovarian cancer cell chemoresistance via inhibiting the PI3K/AKT/mTOR pathway." (PMID 37242538, 2023).
ovarian carcinoma (continued). "The PI3K/Akt/mTOR pathway is activated in approximately 70% of ovarian cancers." (PMID 37569653, 2023). "This may increase the intracellular cisplatin concentration; thus, inhibiting the phosphorylation of Akt, mTOR and Erk, and decreasing the level of Bcl-2, leading to ovarian cancer cells apoptosis." (PMID 37940982, 2023). "Collectively, the mTOR signaling pathway is involved in many crucial biological processes, including ferroptosis, as it is frequently activated in a wide range of tumors, including ovarian cancer." (PMID 37842240, 2023). "Moreover, the downstream 4E-BP1 protein and its phosphorylated expression level were also significantly inhibited by NC, suggesting that NC mainly regulates the malignant phenotype of ovarian cancer cells through Akt/mTOR/4E-BP1 signaling pathway." (PMID 37317923, 2023). "This ceramide-interacting protein, across quaternary membranes, can modulate the mTOR signaling pathway associated with autophagy; LAPTM4B expression has been shown to be a poor prognostic marker in ovarian cancer." (PMID 36937841, 2023). "The PI3K/AKT/mTOR signal pathway was demonstrated to be activated in ovarian cancer." (PMID 37639158, 2023). "mTORC1 is a well known positively regulator of malignancy, and it has been demonstrated that ROS-dependent inhibition of mTOR pathway might result in autophagy, apoptosis and cell death in ovarian cancer cells." (PMID 37304865, 2023). "Furthermore, NC has been proven to be able to regulate the malignant phenotype of ovarian cancer cells by regulating AKT/mTOR pathway." (PMID 37317923, 2023). "In most cases of ovarian cancer, mTOR is phosphorylated (hyperactivated)." (PMID 37958970, 2023). "Considering the relationship between signaling pathways involved in autophagy and function of autophagy in cell apoptosis, it has been shown that autophagy is activated by inhibition of Ras/MAP and PI3K/AKT/mTOR pathways, leading to induced ovarian cancer cell cycle arrest." (PMID 36760166, 2023). "The mTOR downstream regulator p-4EBP1 is a critical prognostic marker in ovarian cancer." (PMID 36593951, 2023). "Taking these results of this study together, it was reasonable to speculate that UBE2S may promote the malignant progression of ovarian cancer cells by promoting the PI3K/AKT/mTOR signaling pathway and thereby promoting cell cycle and inhibiting apoptosis." (PMID 35658829, 2022). "Besides, the cell survival, growth, and proliferation of ovarian cancer id regulated by the PI3K/AKT/mTOR signalling pathway." (PMID 36056690, 2022). "In the present study, our data demonstrated that the expression of p-Akt and p-mTOR was markedly reduced with dezocine treatment, suggesting that dezocine could suppress activation of the Akt/mTOR signaling pathway in ovarian cancer cells." (PMID 36568517, 2022). "The risk model composed of six proteins (GSK3α/β, HSP70, MEK1, MTOR, BAD, and NDRG1) could predict the survival prognosis of ovarian cancer efficiently and had a prominent predictive performance." (PMID 35840928, 2022). "Furthermore, silencing of HIF-1α downregulated AKT/mTOR in ovarian cancer cells, further demonstrating the interplay between these two pathways." (PMID 36230617, 2022). "It was reported that oridonin could suppress metastasis of ovarian cancer via the inhibition of mTOR pathway." (PMID 35813296, 2022). "Besides PTEN deletion alone, deletion of both Lkb1 and Pten genes and mTOR excessive activation result in the development of ovarian carcinoma." (PMID 36539659, 2022). "Also, sEV-AnxA2 protein leads to mesothelial-mesenchymal transition by degradation of the extracellular matrix in the tumor microenvironment to create a pre-metastatic niche for ovarian cancer development through the PI3K/Akt/mTOR pathway." (PMID 36612209, 2022). "The risk model composed of GSK3α/β, HSP70, MEK1, MTOR, BAD, and NDRG1 could predict survival prognosis of ovarian cancer patients efficiently and help disease management." (PMID 35840928, 2022).
ovarian carcinoma (continued). "The PI3K/AKT/mTOR and the RAS/RAF/MEK/ERK kinase signaling pathways are attractive targets for potential therapeutic inhibitors, due to the high frequency of mutations to PTEN, PIK3CA, KRAS and BRAF in several ovarian cancer subtypes." (PMID 35053555, 2022). "UBE2T may regulate the EMT process of ovarian cancer cells through mTOR targets in PI3K-AKT pathway." (PMID 36088429, 2022). "Nevertheless, it remains unknown whether CXCR4-mediated signaling in ovarian cancer is involved in PI3K/Akt/mTOR pathway regulation and impacts EMT and CSC characteristics, invasion and metastasis." (PMID 35681259, 2022). "To explore whether RAD21 promoted malignant biological behaviors in ovarian cancer cells via the Akt/mTOR signaling pathway, we performed rescue experiments." (PMID 35860572, 2022). "Collectively, these results suggest that dezocine might inhibit the expression of CRABP2 by targeting the Akt/mTOR signaling pathway, and ultimately regulate the proliferation and migration of ovarian cancer cells." (PMID 36568517, 2022). "A variety of studies showed that Phosphatidylinositol 3-kinase (PI3K) and Serine/threonine kinase 1 (AKT) are activated in ovarian cancer cells, which positively regulate their downstream genes mTOR, and inhibit cell autophagy, proliferation, apoptosis, and metabolic function." (PMID 35959437, 2022). "Mutations within the PI3K/AKT/mTOR and RAS/RAF/MEK/ERK kinase signaling pathways are characteristic of the low-grade serous (LGSOC), mucinous (MOC), endometrioid (ENOC) and clear cell (CCOC) ovarian cancer subtypes." (PMID 35053555, 2022). "Studies have shown that the combined detection of ASCT2 and p-mTOR can be used as a molecular marker for ovarian cancer, providing reference information for the diagnosis, postoperative follow-up, and targeted therapy of early ovarian cancer patients." (PMID 36523985, 2022). "In combination with cisplatin, BEZ235, an anti-PI3K/mTOR inhibitor, might be a viable therapeutic approach for epithelial ovarian cancer chemoresistance." (PMID 35402264, 2022). "Furthermore, AICAR, an AMPK activator, suppressed the migration and invasion of ovarian cancer cells through an AMPK/mTOR‐dependent pathway." (PMID 36114703, 2022). "Furthermore, MIEF2 (mitochondrial elongation factor 2) increased SREBP1 and SREBP2 by activating ROS/AKT/mTOR signaling to drive the lipid synthesis in ovarian cancer cells." (PMID 35619540, 2022). "It is generally known that the Akt/mTOR signaling pathway, as a classic signaling pathway, is frequently activated in tumors and plays a key role in the malignant transformation of tumors, including ovarian cancer." (PMID 36568517, 2022). "mTOR is a key target in multiple autophagy pathways, and recent studies showed that traditional Chinese medicine can regulate the proliferation, apoptosis, and multidrug resistance of ovarian cancer cells by affecting mTOR-related signaling pathways." (PMID 35959437, 2022). "MTOR has been investigated as a treatment vulnerability in ovarian cancer." (PMID 35840928, 2022). "Because ivermectin suppresses the Akt/mTOR pathway and further mediates apoptosis induction in ovarian cancer cells 21, we speculated that ivermectin can also regulate cellular apoptosis in human UC cells by inhibiting the Akt signaling pathway." (PMID 36185334, 2022). "Furthermore, we evaluated the relationship between NANOG and AMPK/mTOR signalling pathway and examined the clinical and prognostic significance of pAMPK in ovarian cancer." (PMID 36114703, 2022). "Another study based on ovarian cancer reported that apigenin decelerated ovarian cancer development via downregulating ER-mediated PI3K/AKT/mTOR expression, therefore demonstrating its applicability as a potentially effective therapeutic agent for ovarian cancer treatment." (PMID 36144783, 2022).
ovarian carcinoma (continued). "The present study found that HERPUD1 may inhibit PI3K/AKT/mTOR pathway and p38MAPK pathway in ovarian cancer cells, thereby inducing autophagy and preventing the process of EMT." (PMID 36544104, 2022). "Based on these findings, activating the mTOR signaling pathway may be a therapeutic target in patients who are obese and have ovarian cancer." (PMID 34659568, 2021). "Furthermore, as the mTOR inhibitor BEZ-235 displayed a synergistic effect with cisplatin chemotherapy in vitro, combining mTOR inhibitors with standard-of-care chemotherapy was proposed as a viable option for ovarian cancer patients." (PMID 35582310, 2021). "RBM11 promotes ovarian cancer progression through stimulating Akt/mTOR signaling pathways." (PMID 34804951, 2021). "Moreover, we observed that HIF-1α, located downstream of the mTOR, is implicated in LPA-induced DDR2 expression and ovarian cancer cell invasion." (PMID 34065317, 2021). "In this study, we focused on miR-582-3p and combined it with its upstream regulator lncRNA TUG1 and potential downstream target AKT/mTOR to explore the malignant biological behavior of this miRNA in regulating ovarian cancer and to analyze the possible molecular mechanisms." (PMID 34793263, 2021). "Interestingly, the mTOR signaling pathway is reported to play a critical role in the proliferation, development, and progression of human ovarian cancer." (PMID 33968741, 2021). "Further evidence suggests that the neferine anti-angiogenesis mechanism in high-grade serious ovarian carcinoma occurs by inducing autophagy through the inhibition of the mTOR/p70S6K pathway and the suppression of the polarization of M2 tumor-associated macrophages." (PMID 34575981, 2021). "Thus, specific inhibitors targeting mTOR and eIF4E represent promising and valid adjuvants for clinical management of ovarian cancer." (PMID 35582305, 2021). "Thus, TTK inhibition suppressed the progression of ovarian cancer by activating mTOR and further decreasing autophagy." (PMID 34876569, 2021). "Finally, we demonstrated the attenuation effect imparted by apigenin in histamine-mediated ovarian cancer via the PI3K/AKT/mTOR signaling pathway." (PMID 34568014, 2021). "Resveratrol treatment blocks glucose uptake in ovarian cancer cells, triggers starvation-like signalling response (inhibition of Akt/mTOR) and upregulates LMP level resulting in the cytosolic translocation and activation of cathepsin L to promote autophagy-mediated cell death." (PMID 34681206, 2021). "Tumor cell‐intrinsic PD‐L1 promoted basal mTORC1 activity as PD‐L1KO MB49 cells showed decreased activation (phosphorylation) of mTORC1 downstream targets RPS6 and 4E‐BP1 versus control MB49 cells and reduced phosphorylated mTOR, consistent with our prior data from melanoma and ovarian cancer cells." (PMID 33626233, 2021). "Curcumin has been shown to induce cell cycle arrest, autophagy, autophagy flux, cellular senescence and enhanced apoptosis in cervical cancer cells, while promoting protective autophagy and apoptosis through the suppression of AKT/mTOR/p70S6K signalling pathway in ovarian cancer cells." (PMID 34681206, 2021). "In addition, grifolin regulated the AKT/mTOR/S6K signaling transduction in autophagy of human ovarian cancer." (PMID 34641493, 2021). "Therefore, the cisplatin-triggered upregulation of TTK decreased the cisplatin sensitivity of ovarian cancer through the mTOR/autophagy pathway." (PMID 34876569, 2021). "This minireview explores the possibility of targeting mTOR and eIF4E proteins, thus impacting on translation initiation in ovarian cancer, describing the most promising experimental strategies and specific inhibitors that have been shown to have an effect on other kinds of cancers." (PMID 35582305, 2021). "Interestingly, from previous enrichment analysis of the MRPL15 pathway, we predicted that MRPL15 promotes the development of ovarian cancer through the mTOR pathway." (PMID 33934540, 2021).
ovarian carcinoma (continued). "AKT/mTOR pathway plays a vital role in the progression of ovarian cancer." (PMID 35004308, 2021). "In addition, rapamycin inhibited the activity of 70-KDaS6 kinase (P70S6K) downstream of mTOR, demonstrating that resistin promotes the proliferation of ovarian cancer cells by activating mTOR." (PMID 34659568, 2021). "In addition, differences in AKT activity observed in different ovarian cancer cell lines contribute to the cell-specific sensitivity to pharmacological treatment by rapamycin and, more in general, by mTOR inhibitors." (PMID 35582305, 2021). "Our results showed that APG mitigated the HA-induced proliferation of OC cells by regulating the ER-mediated PI3K/AKT/mTOR pathway, which might provide insights into the development of potential treatment strategies for ovarian cancer." (PMID 34568014, 2021). "The correlations of miR-582-3p expression and its interactions with lncRNA TUG1 with AKT/mTOR signaling and ovarian cancer outcomes suggest that the lncRNA TUG1/miR-582-3p/AKT/mTOR axis may be used as a novel prognostic biomarker and therapeutic target in OC." (PMID 34793263, 2021). "However, early increase in tumor ADC values has been reported in subcutaneous ovarian cancer xenografts 3 days post-treatment with a PI3K/mTOR-inhibitor, a pathway of therapeutic interest also in EC." (PMID 34565386, 2021). "Additionally, estrogen and progestin can directly regulate HIF-1α through the PI3K/Akt-mTOR signaling pathway and contribute to tumor metastasis in ovarian cancer." (PMID 34867818, 2021). "Thus, TTK depletion suppresses autophagy in ovarian cancer cells by activating the mTOR signaling pathway." (PMID 34876569, 2021). "There are multiple trials investigating AKT and mTOR inhibitors in patients with ovarian cancer." (PMID 33659215, 2020). "The high prevalence of molecular alterations in the MAPK and PI3K/AKT/mTOR pathways in ovarian carcinomas suggest that targeting Grb2 could be an important and promising therapeutic opportunity." (PMID 32754300, 2020). "The top 5 related genes are TBP, MMP9, MYC, MAPK1, MTOR, which might play important roles in ovarian cancer." (PMID 32958005, 2020). "Inhibition of mTOR by rapamycin analogues (rapalogs) was evaluated as an anti-cancer strategy in clinical trials for renal cell carcinoma, hematopoietic malignancies, ovarian cancer and others." (PMID 32341756, 2020). "On the other hand, knockout of EGFL6 in ovarian cancer cells could reduce the phosphorylation level of Erk, Akt, and mTOR." (PMID 32983976, 2020). "In addition, the Akt/mTOR and Wnt/β-catenin signaling pathway were inhibited by miR-454 in ovarian cancer cells." (PMID 32536825, 2020). "In addition, the Akt/mTOR and Wnt/β-catenin signaling pathways were both inhibited by miR-454 overexpression in ovarian cancer cells." (PMID 32536825, 2020). "As a result, controlling the expression of SIRT1 might be an alternative approach to manage the PI3K/Akt/mTOR pathway in ovarian cancer cells." (PMID 32398958, 2020). "Moreover, overexpression of HVEM significantly promoted the activation of AKT and mTOR in primary ovarian cancer cells further." (PMID 32312328, 2020). "In addition, PKP3 regulated autophagy and invasion of ovarian cancer through MAPK/JNK/ERK1/2/mTOR signaling pathway." (PMID 33088217, 2020). "Existing data prompt the hypothesis that LPA may activate the PI3K/AKT/mTOR pathway through LPAR to directly induce the polarization of monocytes/macrophages to TAMs in ovarian cancer." (PMID 32774171, 2020). "Furthermore, cardamonin-mediated inhibition of ovarian cancer cell growth is achieved through suppression of mTOR and NF-κB transcriptional activity." (PMID 33234722, 2020). "In this study, we found that the knockout of EGFL6 could affect the signaling pathways for ovarian cancer tumorigenesis, by activation of the integrin/Akt/mTOR and MAPK/Erk pathways." (PMID 32983976, 2020).